DKK1 (dickkopf Wnt signaling pathway inhibitor 1)
Diseases named in the same sentence as DKK1 in open-access papers (continued):
Sharing a sentence is not in itself a finding about the gene and the disease.
Arthritis (31 papers, 2010 to 2025). Inflammation of a joint. "A study using the animal arthritis model revealed that DKK-1 blockage causes the sacroiliac joints to fuse, and high levels of functioning DKK-1 appear to be protective of the development of syndesmophytes." (PMID 37261370, 2023). "The potential relevance of Dkk-1 to the structural phenotype of human arthritis is indicated by low serum Dkk-1 levels in SpA and the association between serum Dkk-1 levels and new bone formation in axSpA." (PMID 36308677, 2023). "The expressions of Sost and Dkk1 were transiently increased before the onset of arthritis in adjuvant-induced arthritis models, suggesting that sclerostin expression is associated with the onset of arthritis as well as Dkk1." (PMID 35563281, 2022). "Dkk-1 deficiency in osteolineage cells protects against GC-induced bone loss, whereas it had only minor effects on arthritis." (PMID 31064048, 2019). "The loss of bone in murine models of arthritis can be restored by treatment with antibodies against DKK1, indicating that DKK1 has promise as a novel therapeutic target." (PMID 31019537, 2019). "Treatment with antibodies against DKK1 has restored bone loss in murine models of arthritis, suggesting it has promise as a novel therapeutic target." (PMID 26782930, 2016). "Sost and Dkk1 downregulation has been associated with proteoglycan-induced arthritis in mice, and DKK1 with human AS." (PMID 25889670, 2015). "Alternatively, the unaltered levels may be due to concurrent arthritis-associated bone degradation with erosions that is linked to increased levels of DKK-1 and SOST, which is also an integral part of SpA34." (PMID 33273664, 2020). "Dkk-1 has been strongly implicated in joint remodeling in inflammatory arthritis; blockade of this factor inhibits osteoclastogenesis and bone erosion in in vivo models of RA, even in the presence of persistent joint inflammation." (PMID 20796300, 2010). "Recent research has shown that DKK-1, a potent Wnt pathway inhibitor, is a crucial regulator in experimental models of joint injury and arthritis." (PMID 41019055, 2025). "The expression of Dkk1 appears to play a critical role in determining the trajectory of joint remodelling in arthritis." (PMID 38672170, 2024). "Dkk-1 is abundantly expressed in inflamed joints of destructive and remodelling forms of arthritis, playing an important role in the pathogenesis of RA and PsA." (PMID 38672170, 2024). "Antibody-mediated Dkk1 inhibition resulted in decreased osteoclast formation in mice with arthritis and multiple myeloma." (PMID 33479403, 2021). "TNF-α, IL-17, IL-6, and DKK-1 serum levels were increased, and obestatin and sclerostin serum levels were decreased in the arthritis group compared to the control group." (PMID 32659877, 2020). "In the AIA group compared to CTRL group, expression of Wnt inhibitors SOST and DKK1 was higher at the ankle site before arthritis only (p < 0.01 each), with a trend for a SOST downregulation at day 17 (p = 0.09)." (PMID 29472591, 2018). "Dickkopf-1 (Dkk-1) is a Wnt signaling pathway inhibitor that has been shown to play an important role in joint remodeling, in experimental models of arthritis and in humans." (PMID 32185280, 2017). "Synovial fibroblasts of patients with early inflammatory arthritis that persists as RA express higher DKK1 levels than those from patients with inflamed joints whose arthritis resolves." (PMID 26782930, 2016). "Synovial fibroblasts from patients with VeRA expressed significantly higher levels of DKK1 mRNA compared with those with resolving arthritis." (PMID 26782930, 2016). "Synovial fibroblasts from patients with VeRA expressed significantly higher levels of DKK1 messenger RNA than those from patients with resolving arthritis." (PMID 26782930, 2016). "Analysis of inflamed synovial tissues in animals with arthritis revealed high levels of expression of DKK-1, the potent inhibitor of the Wnt/βcatenin pathway." (PMID 23709258, 2013).
Arthritis (continued). "DKK-1’s function in pathological ossification was highlighted by the notable fusion of the sacroiliac (SI) joints that occurred when it was blocked in an animal model of arthritis." (PMID 41019055, 2025). "DKK1 deficiency in osteoprogenitor cells or osteocytes protects against glucocorticoid-induced bone loss but not arthritis-induced bone loss." (PMID 36768718, 2023). "Serum DKK-1 levels were higher in the arthritis group compared to the control group (P < 0.001)." (PMID 32659877, 2020). "In our study, serum DKK-1 levels increased in the arthritis group and decreased in the MG group." (PMID 32659877, 2020). "The DKK-1 expression has been shown to increase in the experimental arthritis model." (PMID 32659877, 2020). "Serum DKK-1 levels were 23% lower in the MG group when compared to the arthritis group (P < 0.001)." (PMID 32659877, 2020). "DKK1 has been proposed as a biomarker of arthritis in early stages of the disease." (PMID 29584756, 2018). "Targeting this Wnt inhibitor could be interesting in arthritis treatment and easier than sclerostin or DKK1 because its window of upregulation is in declared arthritis." (PMID 29472591, 2018). "In this study, to determine the role of DKK1 in the pathogenesis of early RA, we analysed, for the first time to our knowledge, the expression of DKK1 in synovial fibroblasts from patients with early arthritis that eventually resolved compared with patients whose arthritis developed into RA." (PMID 26782930, 2016). "Chronic exposure to TNF-α promotes the upregulation of sclerostin and in a rat adjuvant-induced arthritis (AIA) model SOST and DKK-1 were overexpressed in the early stages of arthritis onset." (PMID 37887030, 2023). "At the time of arthritis onset, SOST and DKK1 returned to control values, but frizzled related protein 1 (SFRP1), proinflammatory cytokines, and MMPs started to increase." (PMID 29472591, 2018). "We demonstrated that DKK1 and sclerostin were only upregulated before arthritis onset, while SFRP1 was only upregulated after arthritis onset." (PMID 29472591, 2018). "DKK1 expression was increased in FLS and endothelial cells in an animal model of arthritis, and TNF markedly increased the production of DKK1 from cultured FLS." (PMID 30157923, 2018). "A recent study found that in addition to acting as a major driver of bone destruction in arthritis, TNF-α can also upregulate the Wnt antagonist dickkopf-1 (Dkk-1) in FLSs, thereby inhibiting new bone formation in RA patients." (PMID 26821827, 2016). "For this purpose, the genotyping of 552 SNPs located in gene regions of semaphorins 4b, 4d, 4f, DKK1, 2 and 3, sclerostin, OPG, RANK and RANKL was performed using Immunochip from Illumina Inc. in 268 patients from the Princesa Early Arthritis Register Longitudinal (PEARL) study." (PMID 39337893, 2024). "In co-culture constructs, more DKK1 tended to be secreted in co-cultures incorporating fibroblasts from VeRA than in co-cultures from non-inflamed joints and resolving arthritis." (PMID 26782930, 2016). "In experimental arthritis, neutralization of DKK-1 with an antibody inhibited bone erosion without affecting inflammation, whereas the neutralization of sclerostin improved systemic bone loss, but did not affect disease severity or focal bone erosions in the CIA model." (PMID 31394717, 2019). "Before arthritis onset at day 8, OS/BS was inversely correlated with SOST (r = −1, p < 0.02) but not with DKK1 or SFRP1 (r = −0.50, p = 0.45 for both), suggesting that high SOST at day 8 correlated with low osteoblast activity." (PMID 29472591, 2018). "Moreover, expression of DKK-1, a Wnt pathway inhibitor that promotes osteoblast differentiation, was not dysregulated during early arthritis but was increased at day 8, when bone formation had begun, which may indicate the presence of feedback control of the aberrant bone formation." (PMID 26801240, 2016).
Arthritis (continued). "Higher levels of serum DKK1 correlate more with bone erosion in patients with systemic lupus erythematosus (SLE), who are anti-CCP-positive, than in those with either non-erosive arthritis or without arthritis." (PMID 36768718, 2023).
atherosclerosis (30 papers, 2012 to 2025). A disease characterized by the build-up of fatty material and calcium deposition in the arterial wall resulting in partial or complete occlusion of the arterial lumen. "Emerging biomarkers like IL-32, Dickkopf-related protein 1 (DKK-1), and galectin-3 also show potential in further refining risk assessment, particularly for atherosclerosis and myocardial fibrosis in rheumatic diseases." (PMID 40937212, 2025). "Although DKK-1 has emerged as a key mediator in the interaction between inflammation, atherosclerosis, and CV risk, its utility as a prognostic biomarker for CVD in RA patients has not yet been thoroughly evaluated." (PMID 40299461, 2025). "While these pieces of evidence emphasize the significance of DKK1 in atherosclerosis, further investigation is required to unravel its underlying mechanism." (PMID 38175715, 2024). "In particular, DKK1 is positively associated with central obesity, type 2 diabetes and atherosclerosis." (PMID 36410795, 2023). "On the contrary, more recent studies have suggested that Dkk-1 is inversely associated with CAD or atherosclerosis." (PMID 33081636, 2020). "Independent variables were serum DKK1 levels and risk factors for atherosclerosis (age, gender, body mass index, hypertension, dislipidaemia, smoking, sedentarism, HbA1c, GFR, and IMT)." (PMID 25369286, 2014). "In our study, higher DKK1 levels were positively related to cardiovascular disease in T2DM patients independently of the presence of others risk factors for atherosclerosis, and high concentrations of DKK1 were related to abnormal IMT in these patients." (PMID 25369286, 2014). "Additionally, DKK-1 promotes the release of proinflammatory cytokines associated with endothelial dysfunction and atherosclerosis development." (PMID 40299461, 2025). "Furthermore, increased DKK-1 levels associated with atherosclerosis have been correlated with shear stress exerted on endothelial cells, further supporting its role in vascular pathology." (PMID 40299461, 2025). "Background and Objectives: Sclerostin and dickkopf-1 (DKK1), which are Wnt inhibitors, are involved in vascular calcification and atherosclerosis." (PMID 40731833, 2025). "Endothelium-specific knockout of DKK1 (DKK1ECKO/APOE-/-) and endothelium-specific overexpression of DKK1 (DKK1ECTg) mice were constructed to investigate the role of endothelial DKK1 in atherosclerosis and SMC-derived foam cell formation in vivo." (PMID 38904030, 2024). "Our findings reveal a noteworthy positive correlation between DKK-1 levels and cIMT, which serves as an indicative measure of early-stage atherosclerosis." (PMID 37834418, 2023). "DKK1 is elevated in the plasma and lesions of patients with atherosclerosis and type 2 diabetes with cardiovascular diseases." (PMID 36609601, 2023). "These pieces of evidence underscore the crucial involvement of DKK1 in atherosclerosis, although further research is needed to elucidate its underlying mechanisms." (PMID 37742224, 2023). "Currently, DKK1 has been recognized as a biomarker of atherosclerosis due to its significantly increased expression in atherosclerotic lesions, which contributes to endothelial activation, inflammatory responses, coronary atherosclerosis, and acute IS." (PMID 37742224, 2023). "The mechanism linking DKK1 to atherosclerosis involves the activation of JNK signal transduction pathway and the inhibition of canonical Wnt signaling, followed by the activation of the IRE1α and eIF2α/CHOP pathways." (PMID 29921793, 2018). "To accomplish this, we investigated the effect of modulated DKK1 expression on atherosclerosis plaques in ApoE−/− mice and EC apoptosis; and explored the underlying mechanisms in endothelial cells using human umbilical vein endothelial cells (HUVECs)." (PMID 28703797, 2017).
atherosclerosis (continued). "The presence of DKK1 resulted in enlarged and destabilized atherosclerotic lesions and increased apoptosis, while silencing of DKK1 alleviated plaque formation and vulnerability in the whole progression of atherosclerosis." (PMID 28703797, 2017). "Several clinical studies reported that Dickkopf1 (DKK1) plasma levels are correlated with atherosclerosis." (PMID 28703797, 2017). "DKK1 was related to the presence of CVD in T2DM, independently of the presence of risk factors for atherosclerosis." (PMID 25369286, 2014). "DKK-1 plays a crucial role in atherosclerosis and various CVD." (PMID 40299461, 2025). "Currently, DKK1 is considered as a biomarker of atherosclerosis." (PMID 38175715, 2024). "In type 2 diabetes and atherosclerosis, serum DKK1 expression was found to be elevated and speculated that DKK1 was mainly derived from platelet activation." (PMID 36410795, 2023). "Increased Dkk-1 expression is involved in the atherosclerosis process." (PMID 36250025, 2022). "Accordingly, the plasma levels of DKK1 have been found to be high in patients with atherosclerosis." (PMID 33969358, 2021). "Additionally, the Wnt pathway inhibitor DKK-1 was shown to relieve atherosclerosis by affecting the proliferation of vascular smooth muscle cells (VSMCs) cultured in hyperlipidemic serum." (PMID 32880387, 2020). "Furthermore, Dkk-1 regulated the endothelial–mesenchymal transition in aortic ECs, a critical event that drives the initiation and progression of atherosclerosis." (PMID 33081636, 2020). "ER stress can induce atherosclerosis in human umbilical vein endothelial cell via Dickkopf1 (DKK1)." (PMID 29921793, 2018). "Data from animal atherosclerosis studies and in vitro investigations support the observations in humans, suggesting that DKK-1 may be an attractive target for cardiovascular therapy." (PMID 30420710, 2018). "DKK1 has also been considered to play an important role in the development of atherosclerosis." (PMID 30496210, 2018). "DKK-1 and sclerostin, two Wnt pathway inhibitors, are also involved in the atherosclerosis process." (PMID 28553649, 2017). "Therefore, in future experiments we will use EC-specific DKK1 KO mice and macrophage-specific DKK1 KO mice to determine the exact role of DKK1 in atherosclerosis through its action on various cell types." (PMID 28703797, 2017). "DKK-1 serum concentration has already been correlated with the presence of coronary artery calcification and atherosclerosis, and its measurement has been proposed as a simple test that might be useful in CV risk stratification." (PMID 28553649, 2017). "There is also recent data showing a relationship between serum DKK1 and atherosclerosis in humans." (PMID 25369286, 2014). "Our findings indicated that DKK-1 might be released into circulation in advanced atherosclerosis, atherosclerotic plaque destabilization or even rupture." (PMID 23359112, 2013). "However, the paracrine role of endothelial DKK1 in modulating adjacent smooth muscle cells (SMCs) in atherosclerosis remains unclear." (PMID 38904030, 2024). "This excessive DKK1 secretion may contribute to inflammation, monocyte adhesion, and apoptosis of endothelial cells, ultimately, promoting endothelial dysfunction—the initiating step to atherosclerosis." (PMID 33322009, 2020). "Previous studies have indicated a potential connection between plasma levels of Dickkopf-1 (DKK1) and platelet-derived growth factor subunit-B (PDGF-B) with the development of atherosclerosis." (PMID 38175715, 2024). "Epidemiological investigations have indicated a correlation between elevated plasma levels of Dickkopf-related protein 1 (DKK1) and the presence of atherosclerosis." (PMID 37742224, 2023). "In fact, there is a correlation between the DKK-1 molecule (Dickkopf WNT signalling pathway inhibitor 1) and atherosclerosis." (PMID 35634284, 2022).
atherosclerosis (continued). "Several studies correlated elevated DKK1 serum or plasma concentration, with the prevalence of CVD and particularly vascular events, indicating a specific role in atherosclerosis." (PMID 33322009, 2020). "In contrast, increased DKK1, a canonical Wnt inhibitor, in carotid plaques resulted in reduced SMC proliferation, migration and survival adding to the intricacy of Wnt contribution in atherosclerosis." (PMID 33969358, 2021). "Furthermore, DKK1 regulates the de-differentiation of endothelial cells to MSC, a mechanism commonly found in atherosclerosis." (PMID 33322009, 2020). "Indeed, in contrast to patients, Dkk1 expression was almost absent in atheroprone arterial segments in these murine models of atherosclerosis." (PMID 35626694, 2022). "Furthermore, Dkk1 produced by platelets has been shown to control neutrophil invasion in acute lung inflammation via modulating ICAM expression and the inflammatory interaction with endothelial cells during atherosclerosis." (PMID 31921182, 2019).